CDK1 (cyclin dependent kinase 1)
Diseases named in the same sentence as CDK1 in open-access papers (continued):
Sharing a sentence is not in itself a finding about the gene and the disease.
ovarian carcinoma (continued). "Expression analysis using TNMplot.com compared CDK1 levels across normal ovarian tissue (n = 46), ovarian cancer tissue (n = 744), and ovarian cancer metastases (n = 44)." (PMID 41009727, 2025). "Its additional antioxidant and anti-inflammatory properties further enhance its therapeutic appeal, positioning Naringin as a promising alternative to conventional synthetic CDK1 inhibitors for ovarian cancer treatment." (PMID 41009727, 2025). "Our machine learning approaches significantly enhanced the identification of CDK1 as a central regulatory node in ovarian cancer." (PMID 41009727, 2025). "TCGA database analysis via GEPIA confirmed significantly higher CDK1 mRNA expression (|Log2FC| ≥ 0.5) in 426 ovarian epithelial cancer samples compared to 88 normal ovarian epithelial cells (p < 0.01)." (PMID 41009727, 2025). "Several mechanisms contribute to the dysregulation of CDK1 in cancer, particularly in epithelial ovarian cancer." (PMID 41009727, 2025). "Multiple network centrality measures consistently highlighted CDK1 as the most influential hub gene, underscoring its central role within the ovarian cancer interactome." (PMID 41009727, 2025). "Transcriptome profiling combined with machine learning inference and in silico simulations identified CDK1 as a critical regulatory hub in epithelial ovarian cancer." (PMID 41009727, 2025). "Upon WDR62 knockdown, the expression of cell cycle-related proteins CDK1 and C-Myc decreased in ovarian cancer cells, and the cell proliferative capacity was decreased." (PMID 40369663, 2025). "Despite advances in surgical techniques and chemotherapeutic agents, the five-year survival rate for advanced-stage ovarian cancer remains below 30%, highlighting the urgent need for novel therapeutic strategies targeting key molecular drivers like CDK1." (PMID 41009727, 2025). "Our investigation revealed not only CDK1’s involvement in ovarian cancer but also its overexpression in cisplatin-resistant cells, suggesting its role in treatment resistance." (PMID 41009727, 2025). "While several studies have investigated the role of cell cycle regulators in ovarian cancer, there exists a significant knowledge gap regarding the potential of specifically targeting CDK1 in epithelial ovarian cancer." (PMID 41009727, 2025). "Cyclin-dependent kinase 1 (CDK1) has emerged as a master regulator of ovarian cancer cell cycle progression and survival, with growing evidence supporting its therapeutic targeting." (PMID 41009727, 2025). "The silencing of UBE2C in ovarian cancer cell lines markedly reduces cell proliferation and augments apoptosis, primarily by inducing G2/M phase arrest and reducing CDK1 expression." (PMID 39033780, 2024). "We initiated the investigation by assessing CDK1 levels in both ovarian cancer and normal ovarian epithelial cells, revealing an elevated expression of CDK1 in ovarian cancer cells." (PMID 37986001, 2023). "Although these results were generated in two ovarian cancer cell lines and a single ovarian cancer transgenic mouse model, our data provide biological evidence for future clinical trials of CDK1 inhibitors in OC." (PMID 37569750, 2023). "Through its regulation of CDK1, HADHA influences critical cellular processes in ovarian cancer, providing insights into its pathogenic mechanism." (PMID 37986001, 2023). "In a relevant study, the depletion of UBE2C was found to reduce the malignancy of ovarian cancer and reverse resistance to cisplatin by downregulating CDK1." (PMID 37986001, 2023). "A study of ovarian cancer cells showed that high UBE2C expression correlated with expression of CDK1." (PMID 37377594, 2023). "To shed light on the precise regulatory mechanism by which HADHA and CDK1 are intertwined in mediating ovarian cancer, we probed into the UPS." (PMID 37986001, 2023).
ovarian carcinoma (continued). "In summary, our current work demonstrated that unequivocally establishes that HADHA plays a pivotal role in promoting tumorigenesis in ovarian cancer through its modulation of CDK1." (PMID 37986001, 2023). "Overall, our results demonstrate that the inhibition of CDK1 activity by RO-3306 effectively reduces cell proliferation and tumor growth, providing biological evidence for future clinical trials of CDK1 inhibitors in ovarian cancer." (PMID 37569750, 2023). "Conversely, CDK1 displayed pronounced upregulation in ovarian cancer samples relative to normal samples across multiple datasets, including GSE40595, GSE36668, GSE69428, GSE54388, and GSE26712." (PMID 37986001, 2023). "A previous study from our group demonstrated that UBE2C was highly expressed in ovarian cancer tissues and promoted ovarian cancer progression by upregulating CDK1." (PMID 35804892, 2022). "To investigate the roles of TTK, NEK2, and CDK1 overexpression, we mined the TCGA’s ovarian cancer genomics data via the cBioportal website." (PMID 34072728, 2021). "Further, a higher expression level of CDK1 was correlated with poor prognosis of ovarian cancer patients." (PMID 34745968, 2021). "The Oncomine database was used for the expression analysis of TTK, NEK2, and CDK1 in ovarian cancer and normal samples." (PMID 34072728, 2021). "The findings showed that in different cancers, CDK1 was overexpressed, and its expression was greatly increased in ovarian cancer patients." (PMID 34072728, 2021). "Collectively, our study suggested that TTK, NEK2, and CDK1 are novel biomarker signatures of ovarian carcinoma and an attractive target for NSC777201 with consequent anticancer implications." (PMID 34072728, 2021). "CDK1 expressed a significantly higher level in ovarian cancer tissues, compared with normal tissues." (PMID 34745968, 2021). "For example, Melk can enhance the bortezomib resistance of natural killer/T-cell lymphama through EZH2, while the infection of CDK1 expression and activity reduced ovarian cancer growth." (PMID 33956061, 2021). "Our previous research also proved that CDK1 participates in ovarian cancer tumorigenesis and progression." (PMID 33483472, 2021). "CDK1 was significantly increased in ovarian cancer, and knocking down CDK1 reduced the growth of ovarian cancer cells." (PMID 33178832, 2020). "Yet, in ovarian cancer, GSK3B activity was linked with cell proliferation, and overexpression of its active form can induce CDK1 expression and facilitate cell proliferation." (PMID 31108958, 2019). "The present study aimed to analyze the relationship between CDK1 and the proliferation and apoptosis of ovarian cancer cells, investigate its molecular mechanism preliminarily." (PMID 28899430, 2017). "In our previous study, high levels CDK1 were detected in almost all ovarian cancer tissues, which were not related with the clinical stage and histological differentiation of ovarian cancer." (PMID 28899430, 2017). "MiR‐490‐3p plays a tumour suppressor role in epithelial ovarian cancer by targeting CDK1 regulation and influencing SMARCD1 and cyclin D1 (CCND1) expressions." (PMID 28598010, 2017). "Upregualtion of CDK1 protein was also reported to be relevant to the development and progress of ovarian cancer." (PMID 28899430, 2017). "In present study, specific short-hair RNA plasmids of CDK1 was used to knockdown the expression of CDK1 in the human ovarian cancer SK-OV-3 and OVCAR-3 cells respectively." (PMID 28899430, 2017). "Cyclin B1, known to interact with and regulate the activity of Cdk1, is mainly expressed in the cytoplasm of ovarian cancer cells." (PMID 27385216, 2016).
ovarian carcinoma (continued). "Reanalysis of the microarray results revealed up-regulation of Cdk1 expression in the ovarian cancer cell lines." (PMID 27385216, 2016). "In conclusion, cytoplasmic Cdk1 expression which was elevated in ovarian cancer predicts a poor overall survival." (PMID 27385216, 2016). "When ovarian cancer cell lines were treated with si-Cdk1 for 72 h, the sub-G1 population of OVCAR-3, SK-OV-3, and OVCA-433 cells was remarkably larger than that of si-negative control transfected cells." (PMID 27385216, 2016). "In this study, we found interesting results that the expression of cytoplasmic cdk1 increased in ovarian cancer." (PMID 27385216, 2016). "We selected si-Cdk1#2, which showed the strongest apoptotic effects, and observed its effects on various ovarian cancer cell lines." (PMID 27385216, 2016). "When the expression and activity of Cdk1 were inhibited by si-Cdk1 or RO-3306 which is a potent Cdk1 inhibitor, the growth of ovarian cancer was diminished." (PMID 27385216, 2016). "But, we demonstrated that expression levels of cytoplasmic Cdk1 were increased in the results from ovarian cancer patient's tissue microarray (n = 249) and ovarian cancer cell lines (n = 14)." (PMID 27385216, 2016). "In order to determine if Cdk1 protein elevation shows clinicopathologic characteristics, immunohistochemistry (IHC) of ovarian cancer tissue samples was performed and classified by histology." (PMID 27385216, 2016). "An immunohistochemical analysis of 119 human ovarian cancer samples showed that the expression of CDK1 is a prognostic factor in epithelial ovarian cancer, and knockdown of CDK1 promoted apoptosis and increased the sensitivity of epithelial ovarian cancer to chemotherapy drugs." (PMID 41541703, 2026). "CDK1, a crucial regulator of the G2/M transition, is frequently overexpressed in in various cancers, CDK1 inhibitors, such as RO-3306, have shown potential in inhibiting tumor cell proliferation in ovarian cancer." (PMID 40286596, 2025). "Additionally, CDK1 exerts a proapoptotic function, sensitizing ovarian cancer cells to paclitaxel and overcoming resistance when co-administered with duloxetine." (PMID 40746552, 2025). "This positions CDK1 as a central regulatory hub in ovarian epithelial cancer." (PMID 41009727, 2025). "The last TAAr is the ubiquitin-conjugating enzyme E2C (UBE2C, gene: UBE2C), which emerges as a pivotal oncogene in ovarian cancer, significantly influencing tumor malignancy and resistance to cisplatin chemotherapy by interacting with Cyclin-Dependent Kinase 1 (CDK1)." (PMID 39033780, 2024). "AT-I can downregulate the expression of cyclin-dependent kinases (CDK1) in ovarian cancer SK-OV-3 and ovarian carcinoma (OVCAR)-3 cells through the PI3K/AKT pathway, which leads to cell cycle arrest in the G2/M phase, and plays an important role in the proliferation inhibition of tumor cells." (PMID 38543015, 2024). "Additionally, xenograft tumor models were developed to visualize the impacts of HADHA/CDK1 on ovarian cancer progression." (PMID 37986001, 2023). "In this study, we investigated the effect of CDK1 expression on the prognosis of patients with ovarian cancer and the anti-tumorigenic effect of RO-3306 in both ovarian cancer cell lines and a genetically engineered mouse model of high-grade serous ovarian cancer (KpB model)." (PMID 37569750, 2023). "Our results indicate that the inhibition of CDK1 by RO-3306 significantly increases cellular ROS production and decreases mitochondrial membrane potential, accompanied by changes in cellular stress-related proteins in ovarian cancer cells." (PMID 37569750, 2023). "Likewise, in certain cancer types, including tumors of the breast, lung, and colon, high levels of CDK1 have also been associated with poor prognosis, while upregulation of CDKN3 has been underscored as an independent poor prognostic factor in ovarian cancer." (PMID 37509358, 2023).
ovarian carcinoma (continued). "Finally, a panel of rescue experiments were conducted to illustrate the roles of HADHA/CDK1 in ovarian cancer development." (PMID 37986001, 2023). "Additionally, three proteins previously shown to be associated to ovarian cancer prognosis were added from the literature (i.e. CT45, CDK1 and CLDN3)." (PMID 36544142, 2022). "In summary, we reported that treatment with ghrelin specifically promoted cisplatin sensitivity by inducing phosphorylation of CDK1 at Tyr15 and Thr14 via inhibiting the phosphorylation of p38, and subsequently promoting S phase cell cycle arrest in the HO-8910 PM ovarian cancer cell line." (PMID 34789301, 2021). "In addition to the PPI network, ingenuity pathway analysis also implicate TTK, NEK2, and CDK1 in the elevated salvage pyrimidine and pyridoxal pathways in ovarian cancer." (PMID 34072728, 2021). "This indicates that suppression of CDK1 can reduce ovarian cancer growth." (PMID 34072728, 2021). "In addition, DLEU1 aggravates the progression of ovarian cancer through interacting with miR-490-3p to modulate CDK1 expression." (PMID 34113562, 2021). "CDK1 is an important cell cycle regulator and is involved in breast, lung, and ovary carcinomas." (PMID 32093341, 2020). "Overexpression of CDK1 was detected in ovarian cancer tissues, which was related with the worse prognosis, and could be a potential molecular biomarkers of epithelial of ovarian cancer." (PMID 28899430, 2017). "Because of high expression of CDK1 in ovarian cancer tissue, there was study suggested that aberrant expression of CDK1 could be an early event of ovarian cancer." (PMID 28899430, 2017). "Based on present results, further study performed about CDK1 protein functions might be helpful to illuminate the molecular mechanism of the carcinogenesis of ovarian cancer." (PMID 28899430, 2017). "In summary, we believe that DLEU1 promotes the pathogenesis and development of epithelial ovarian cancer through its interaction with miR‐490‐3p, thereby altering the expression of the miR‐490‐3p target genes, that is, CDK1, CCND1 and SMARCD1, as well as the expression of MMP2, Bcl‐xLand P70S6K." (PMID 28598010, 2017). "However, lysosomal degradation of CDK1 was shown in different low tumorigenic carcinoma cell lines after DNA damage and CDK1 downregulation was reported in ovarian cancer in response to SAHA treatment." (PMID 29100385, 2017). "Moreover, the involvement of CDK1 in tumorgenesis was postulated in various types of cancer, including laryngeal cancer and ovarian cancer cells." (PMID 28969025, 2017). "In addition, Cdk1 knockdown or treatment of Cdk1 inhibitor resulted in inhibition of cell growth via G2/M arrest and apoptosis in ovarian cancer cell lines." (PMID 27385216, 2016). "Therefore, Cdk1 has potential as a desirable candidate gene for effective treatment of ovarian cancer and is expected to effectively inhibit ovarian cancer in combination with chemotherapeutic agents." (PMID 27385216, 2016). "And, that cytoplasmic Cdk1 expression is correlated with ovarian cancer patient's survival rate." (PMID 27385216, 2016). "Furthermore, all 14 ovarian cancer cell lines maintained in our laboratory were found to have elevated levels of Cdk1 expression." (PMID 27385216, 2016). "When all is said and done, we imply that cytoplasmic Cdk1 expressed in ovarian cancer can be activated and this altered expression of cytoplasmic Cdk1 might influence in ovarian cancer growth." (PMID 27385216, 2016). "As a result from this study, high expression of cytoplasmic Cdk1 could be a common characteristic of ovarian cancer, which is different from normal ovarian epithelial cells and be associated with patient's prognosis." (PMID 27385216, 2016).
ovarian carcinoma (continued). "Finally, these results suggested that cytoplasmic Cdk1 plays a crucial role of cancer growth in epithelial ovarian cancer." (PMID 27385216, 2016). "Also, Inhibitory phosphorylation form of Cdk1 (pTyr15) in epithelial ovarian cancer cell lines was increased in nucleus than in cytoplasm." (PMID 27385216, 2016). "But, the precise mechanism whereby cytoplasmic Cdk1′s activity modulates ovarian cancer growth remains unknown." (PMID 27385216, 2016). "Also, the expression of Cdk1 was increased in ovarian cancer cell lines and Gene Expression Omnibus datasets." (PMID 27385216, 2016). "In addition, expression levels of phospho-BRCA1 (Ser1524) and BRCA1 as a key regulated protein in DNA double-strand repair mechanism and homologous recombination were diminished in si-Cdk1 transfected ovarian cancer cell lines, in a time-dependent manner." (PMID 27385216, 2016). "Therefore, it is possible that the high activity of cytoplasmic Cdk1 in ovarian cancer depends on cytoplasmic cyclins and reduced inhibitory phosphorylation." (PMID 27385216, 2016). "In addition, although the average cytoplasmic Cdk1 IHC score in ovarian cancer TMA slide was relatively low at 1.17, it was 3.44-fold higher than the average score of 0.34 in normal tissues." (PMID 27385216, 2016). "This indicates that ovarian cancer also maintains a high level of Cdk1 expression and activity." (PMID 27385216, 2016). "Whereupon, it is also highly possible that recurrence and malignancy could be higher in ovarian cancer with higher levels of Cdk1 expression and activity, and prognosis of patients could be poor as a result." (PMID 27385216, 2016). "According to these observations, ovarian cancer cells could be negatively affected by inhibition of Cdk1 expression, because of apoptosis and DNA damage." (PMID 27385216, 2016). "The inhibition of Cdk1 expression and activity reduced ovarian cancer growth." (PMID 27385216, 2016). "Interestingly, compared with parental cells, ovarian cancer cells resistant to flavopiridol and cisplatin showed the increased expressions of CDK1, cyclin D3 and Rb, decreased expressions of cyclin B, and equal expressions of cyclin A, cyclin E, CDK2, CDK4." (PMID 25962959, 2015). "A study has shown that dasatinib may enhance paclitaxel sensitivity by suppressing B cell lymphoma-2 and cyclin dependent kinase 1 expression in ovarian cancer cells via a p27(Kip1)-dependent process." (PMID 25975261, 2015). "We initially performed immunoblotting to detect Cdk1 and Cdk2 in ovarian cancer cell lines." (PMID 26204491, 2015). "Consequently, we put forth the hypothesis that HADHA facilitates the progression of ovarian cancer by upregulating CDK1, both in vitro and in vivo." (PMID 37986001, 2023). "Thus, DLGAP5 knockdown could attenuate cell growth and induce apoptosis via cyclin-dependent kinase 1/cyclin D1/Bcl-2 signaling in ovarian cancer cells." (PMID 36499051, 2022). "Thus, we hypothesized that circ-NOLC1 could promote ovarian cancer development by binding with miRNAs that inhibit the translation of CDK1 and RhoA." (PMID 33483472, 2021). "Thus, it is highly probable that since ovarian cancer shows high levels of Cdk1 expression and activity, ovarian cancer could exhibit resistance to DNA damage agents due to increased BRCA activity by Cdk1." (PMID 27385216, 2016). "In addition, the use of a CDK1 inhibitor could inhibit the growth of ovarian cancer." (PMID 41541703, 2026). "In ovarian cancer (OC), circ-NOLC1 binds to ESRP1 and upregulates CDK1 and RhoA expression to promote OC progression." (PMID 40864495, 2025). "It has been demonstrated to suppress CDK1 expression, control cell cycle, and limit proliferation in human ovarian cancer cells via the PI3K/Akt signaling pathway, leading to anti-ovarian cancer actions." (PMID 37241729, 2023). "Taken together, our findings suggest that CDK1 and CDK2 regulate the activation of MLK3 and JNK during G1/S and G2/M phases to control ovarian cancer cell division." (PMID 35843311, 2022).